HIF1A (hypoxia inducible factor 1 subunit alpha)
Diseases named in the same sentence as HIF1A in open-access papers (continued):
Sharing a sentence is not in itself a finding about the gene and the disease.
cancer (continued). "Pharmacological inhibition of HIF-1α and ROS, two main drivers of glycolysis in CAFs, partially revert the glycolytic phenotype by rescuing IDH3α and downregulating MCT4 expression in fibroblasts and reduce aggressiveness of ADT carcinoma cells." (PMID 35814364, 2022). "Although many factors contribute to HIF-1α stabilization, ROS, produced homogeneously by photon irradiation, have been more recently involved in this mechanism, with the fastest stabilization of HIF-1α in Cancer Stem Cells (CSCs) compared to non-CSCs." (PMID 34359734, 2021). "HIF1α and PML-RAR; genes that participate in cancer promotion and metastasis." (PMID 34944416, 2021). "Since it has been shown that LINK-A controls HIF-1α stabilization through interaction with PTK6 and LRRK2 in cancer cells, this prompted us to evaluate whether PTK6 and LRRK2 mediate increased LINK-A–induced HIF-1α expression in RA FLSs." (PMID 34877935, 2021). "Despite the intensive interests, MYC and HIF1α have not been successfully targeted for clinical cancer treatment." (PMID 33572152, 2021). "In vitro experiments in various cancer cell lines and animal models with PC-3 and OVCAR3 showed that treatment with apigenin resulted in a reduction of angiogenesis and a decrease in the levels of the HIF-1α protein and its mRNA." (PMID 34200019, 2021). "In this study, we performed dual HIF-1α and HIF-2α inhibition using Acriflavine and S1P-signaling inhibition with FTY720 in an autochthonous ccRCC mouse model and human ccRCC cell lines, and showed evidence of a strong anti-cancer effect." (PMID 34638286, 2021). "Adaptation of cancer cells to the hypoxic microenvironment is regulated through physiological responses to hypoxia that are mediated by hypoxia-inducible factors (HIF), namely HIF-1α and HIF-2α." (PMID 33644043, 2021). "HIF-1α a prime regulator of cell signaling in the absence of oxygen was upregulated in cancer-bearing rats." (PMID 34447314, 2021). "Since ID1 is a well-established oncoprotein that promotes cancer cell survival and proliferation, we hypothesize that the increase of ID1 may confer adaptive resistance to HIF1α-targeted inhibition." (PMID 34820369, 2021). "The reduction of the PDK1 levels can partially be explained by the DCA-stimulated degradation of HIF-1α in cancer cells, while HIF-1α does not seem to play a role in reducing the PDK1 protein levels in L6 myotubes." (PMID 34445316, 2021). "PSMD10 has been demonstrated to promote the proliferation, invasion, metastasis and angiogenesis of cancer cells through PI3K/Akt/HIF-1α signaling, which may depend on promoting the degradation of HIF-1α." (PMID 35095928, 2021). "Additionally, in cancer cells, TGF-β is engaged in several additional signaling pathways such as the I3K/Akt or MAPK pathways that control NF-kB, HIF-1a, or other redox-sensitive transcription factors." (PMID 34947978, 2021). "At the transcriptional level, hypoxia induced factor-1α (HIF-1α) and the genes under its control, such as VEGF, which functions as the most important angiogenesis growth factor that promotes cancer progression, are the main targets of melatonin for inhibition of angiogenesis." (PMID 34199311, 2021). "Therefore, HIF-1α can influence PKM2 and cellular reprogramming, demonstrating the intricate nature of PKM2 in cancer and beyond." (PMID 33503959, 2021). "Interestingly, HSF1, HIF1α, RXR, and VDR have been described as CAF modulators in various cancer types." (PMID 33670717, 2021). "Chronic hypoxia was found to downregulate FANCD2 in cancer cells independent of the HIF-1α expression, resulting in an impaired FA pathway, contributing to genomic instability." (PMID 33796526, 2021). "Regarding HIF-1α mRNA expression, the pattern appeared more similar to that of AQP3 protein expression, which follows what has been described in the literature for cancer cells." (PMID 33917751, 2021).
cancer (continued). "So far, we cannot definitely say which of the two transcription factor, NRF2 or HIF-1α, is responsible for proliferation under hypoxic conditions although overexpressed HIF-1α failed to rescue cancer growth after NRF2 KD." (PMID 33441543, 2021). "Whether MIIP regulates HIF-1α and HIF-2α through these 2 mechanisms simultaneously, differentially, or in a cancer-type dependent manner remains to be investigated." (PMID 34931765, 2021). "In addition, Remodelin was shown to weaken doxorubicin resistance and suppress hypoxia in cancer through NAT10/(VIM/TWIST/CDH1) and NAT10/(HIF1A/HIF2A) respectively." (PMID 33723305, 2021). "For this reason, inhibition of HIF-1α, or HIF-1α-mediated metabolism pathway, may represent a potential treatment for cancer." (PMID 34944758, 2021). "In many aggressive cancers, the LDH-5 isoform is upregulated, probably as a consequence of the transactivation of the LDHA promoter by transcription factors responsible for the metabolic rewiring of their cells, such as c-myc and HIF-1α." (PMID 33804985, 2021). "Moreover, it was found that celecoxib induces apoptosis of cancer cells via activating PPARγ, inhibits the expression of the EGFR-downstream signaling pathway, as well as HIF-1α activity and HIF-1α-dependent molecules, e.g., VEGF." (PMID 34577574, 2021). "HIF-1α and GATA3 form a complex that enhances cancer cell invasiveness." (PMID 34912753, 2021). "Some studies have also proposed that the combined inhibition of HIF-1α and GLUT1 could be a promising cancer therapeutic strategy." (PMID 34281558, 2021). "HIF-1a and TGF-β1 are EMT regulators that also regulate L1CAM expression in cancer cells." (PMID 34078883, 2021). "Also, SCG2 inhibited expression of HIF‐1α in cancer cells by interacting with VHL, a ubiquity‐degrading enzyme of HIF‐1α." (PMID 34160138, 2021). "This study clearly highlights the involvement of HIF-1α in the detection, signaling, and repair of the DNA Double-Strand-Breaks in response to both irradiations under hypoxia, in two HNSCC cell lines and their subpopulation of Cancer-Stem Cells." (PMID 34359734, 2021). "Moreover, several cancer-promoting factors, such as Bclaf1, PRMT1, and angiotensin II, have been reported in the transcriptional regulation of HIF-1α." (PMID 33716751, 2021). "Although PVT1 has been shown to regulate HIF1α transcriptionally by binding with KAT2A and play oncogenic roles in cancers, we demonstrated that PVT1 could bind HIF2α and stabilize HIF2α protein, thus promote tumorigenesis and angiogenesis." (PMID 34321604, 2021). "Interestingly, Quercetin increased the accumulation of HIF1α in healthy cells, showing improvement in the therapeutic index of DOX through its opposite effects on HIF1α in healthy and cancer cells." (PMID 33918290, 2021). "Providing that memantine decreased the master oncogenic regulators like HIF1A, B-catenin and PKM, our results conclude that memantine could be used in targeting cancer cell metabolism." (PMID 34121969, 2021).
cancer (continued). "Reports documenting that SRGN promotes cancer cell aggressiveness and metastasis through several signaling pathways, including CD44/NF-κB/CLDN1 axis, HIF-1α/SRGN axis, and SRGN/TGFβ2 axis, may further support our observations presented here." (PMID 34059749, 2021). "Through S1P receptor activation, S1P could stabilize HIF-1α and HIF-2α in various cancer cell lines including renal clear cell carcinomas." (PMID 34502385, 2021). "Based on the findings from the cancer and I/R studies, both of which are pathological situations, HIF-1α is not rapidly degraded by the proteasome as in normal tissue." (PMID 33466614, 2021). "The new features revealed by the gene module analysis were the up-regulation of cancer-related modules including calcium and HIF1α signaling, pathways of glycolysis, cancer, and negative regulation of apoptosis." (PMID 33925224, 2021). "In addition, HIF-1α triggers expression of “don’t eat me” proteins, including CD47 and PD-L1, on the surface of cancer cells allowing them to escape phagocytosis and adaptive immunity." (PMID 35127700, 2021). "In cancer cells, under normoxia, EZH2 is recruited directly to the HIF-1α promoter and inhibits HIF-1α expression, whereas under hypoxia, this inhibitory effect is weakened, leading to unregulated HIF-1α expression." (PMID 34737746, 2021). "Both HIF-1α and HIF-2α seemed to be equally crucial in cancer invasion and aggressiveness." (PMID 34824343, 2021). "In addition, TGF-β2 secreted by CAFs cooperate with HIF-1α derived from the hypoxic TME to activate the Hedgehog pathway, which promotes cancer cell stemness and resistance to chemotherapy." (PMID 33732706, 2021). "Although, HIF-1α can promote cell-cycle arrest by inhibiting c-Myc activity, HIF-2α has been shown to stimulate the progression of the cell-cycle and neoplastic growth of cancer cell, via functional enhancement of c-Myc." (PMID 33472628, 2021). "VHL, which regulates HIF-1α and 2α and other types of cancer-related genes, has been shown to be extensively absent in renal cancer cells." (PMID 34604067, 2021). "Furthermore, in mouse cancer models, the removal of UBE2O weakened the intra-tumoral vascularization and expression of neovascularization genes, including HIF1a targets." (PMID 34451875, 2021). "Melatonin-induced prevention of HIF-1α nuclear translocation and the subsequent decrease in VEGF expression may hinder the angiogenic gene complex consisting of HIF-1α, phosphor-STAT3, and CBP/p300 in cancer." (PMID 33406787, 2021). "Since Y6 and ursolic acid can restrict HIF-1α expression in both normoxic and hypoxic conditions, they may potentially block HIF-1α-related signaling in cancer." (PMID 34575983, 2021). "Thereafter, in situ post-radiotherapy monitoring (one day, three days, and seven days post-treatment) of the 3D cell cultures via quantification of (i) HIF-1a secretion by the cancer cells; (ii) Live/Dead and apoptotic profiles, and (iii) ECM (collagen-I) secretion by the cancer cells took place." (PMID 34885188, 2021). "Additionally, as cancer consumes glucose within the TME, it secretes lactate creating an acidic environment that aids in the stabilization of HIF-1α mRNA." (PMID 34987525, 2021). "Since PTBP3 can activate the translation of HIF-1α mRNA, a BCRT1/PTBP3/HIF-1α feedback loop may control cancer progression." (PMID 34298879, 2021). "mRNA levels of HIF1α can be a useful indicator of health status due to BOO and may facilitate prediction of prognosis in patients with cancer." (PMID 34162983, 2021).
cancer (continued). "Cancer cells also produce interleukin-6 (IL-6) to activate signal transducer and activator of transcription 3 (STAT3) to induce hypoxia-inducible factor-1alpha (HIF-1α), VEGF, and C-C motif ligand (CCL) 5 expression in lymphatic ECs (LECs) within premetastatic niches to promote metastasis." (PMID 36046433, 2021). "Its molecular mechanism may be related to inhibiting the expression of HIF-1a and HSP90, increasing the ROS level and inducing apoptosis of cancer cells." (PMID 33457406, 2020). "Although HIF-1α constitutes a potent hypoxic response mechanism, other pathways such as the phosphatidylinositol 3-kinases (PI3K)-Akt-mTOR pathway and Wnt/ß–catenin also participate in the adaptation of cancer cells to hypoxic conditions." (PMID 32024881, 2020). "More precisely, the level of PFKFB3 but not that of other PFKFBs, as a target of HIF-1α that displays the highest phosphofructo-2-kinase activity, is significantly elevated in aggressive cancers, such as PDAC, colon cancer, and breast carcinoma." (PMID 33256814, 2020). "Notch can also induce HIF-1α, NF-κB, and miR-200 for EMT induction in various cancer cell lines." (PMID 32322559, 2020). "This domain serves as an interaction platform for non-canonical binding partners of β-catenin, such as Hif1α, which is involved in adapting cancer cells to sugar metabolism." (PMID 32415084, 2020). "Compound 13b demonstrated the best potent inhibitory effect against HIF-1α activity but was not cytotoxic to cancer cells." (PMID 32824664, 2020). "A3R is also reported to increase HIF-1α through a non-transcription-dependent, non-HIF-1α oxygen-dependent degradation mechanism in several cancer cell lines." (PMID 32351498, 2020). "Cell molecules including transcription factors (e.g., NF-κB, STAT3, HIF1α) and cytokines (e.g., IL-6, Cox-2, and TNF-α) coordinate together and lead to the amplification of inflammation and creation of a suitable environment for cancer growth." (PMID 32758196, 2020). "Several drugs inhibiting HIF-1α protein synthesis such as Topotecan, CRLX101, a nanoparticle conjugate containing the payload camptothecin (CPT) are undergoing clinical investigation for HIF-overexpressing cancers (NCT01652079)." (PMID 32824207, 2020). "HIF-1α and HIF-2α are responsible for the transcriptional activity of some genes involved in the maintenance and evolution of cancer stem cells (CSCs), such as POU domain, class 5, transcription factor 1 (POU5F1), delta-like 1 Homologue (DLK1), CD133, and CD24." (PMID 32751958, 2020). "Additionally, our results indicated the OA/FABP5/HIF-1α axis facilitated HCC cell proliferation, indicating this axis is a promising therapeutic target for reversing cancer-related lipid metabolism reprogramming." (PMID 33128030, 2020). "It is noteworthy that HIF1α and BMP4 have both been reported not only to promote MUC5AC expression, but also to upregulate expression of OCT4, which is a pluripotency gene and a marker for lung and cancer stem cells." (PMID 33015064, 2020). "Interestingly, the PERK pathway was also shown to inhibit HIF-1α translation and thus prevent HIF-1 signaling in cancer cells." (PMID 32190062, 2020). "The details of the mechanism of YC-1 are not clear but YC-1 suppresses the activity of HIF-1α in cancer cells, and in this study, the decrease of HIF1-α protein in YC-1-treated cells was confirmed." (PMID 32367141, 2020). "In most of the cancer cells, the PI3K (phosphoinositide 3-kinase)/mTOR (mammalian target of rapamycin) signaling pathway is activated by insulin, thereby up-regulating PKM2 expression through HIF1α-mediated transcription of the PKM gene." (PMID 32195169, 2020). "HIF‐1α activates the COX‐2 signaling axis and is crucial in cancer cell stemness." (PMID 32991066, 2020).
cancer (continued). "HIF-1α is a nuclear protein with transcriptional activity in the hypoxic environment and HIF-1α can activate downstream genes participating in crucial aspects of cancer biology, including angiogenesis, cell survival, glucose metabolism and invasion." (PMID 32644049, 2020). "In addition, we added HIF1A and LOX as additional targets due to their relevance in cancer aggressiveness and adaption of ECM to promote invasion." (PMID 31959767, 2020). "Gene silencing of HIF-1α, the oxygen-sensitive subunit of the heterodimeric transcription factor HIF-1 (HIF-1α/HIF-1β), suppresses the phosphorylation of STAT3 in fibroblasts, while ouabain reduces HIF-1α levels in cancer and smooth muscle cells." (PMID 33101052, 2020). "At the molecular level, these substances reduce expression of the epithelial markers E-cadherin, HIF-1α, and/or TGF-β1 and increase expression of the mesenchymal markers vimentin and N-cadherin, which inhibit cancer cell migration and invasion, therefore downregulating the EMT process." (PMID 32377312, 2020). "Furthermore, supplementation of CoCl2 in the co-culture upregulated HIF-1α and increased VEGF production in cancer cells and EC growth." (PMID 32531897, 2020). "Nicotine can regulate HIF1A expression in several types of cancer, and therefore we suspected that nicotine might affect YAP expression through a HIF1A-mediated mechanism." (PMID 32894161, 2020). "Once in the nucleus, PKM2 can promote the transcription of target genes, such as HIF-1α targeted expression of GLUTs, PKM2, LDH-A, and VEGF-A, leading to the promotion of growth, positive feedback regulated-glycolysis and angiogenesis in cancer cells." (PMID 32631382, 2020). "Additionally, a growing body of evidence supports the role of lncRNAs in the hypoxic and normoxic regulation of HIF and its subunits HIF-1α and HIF-2α in cancer." (PMID 32640630, 2020). "Our findings verified that HMGB1 induced cisplatin resistance in HCC cells via HIF-1α, enriched the studies on the role of HMGB1 and HIF-1α in promoting cancer, and it will be interesting to further determine their synergism to induce cisplatin resistance in vivo." (PMID 32328193, 2020). "Furthermore, the link between HIF-1α accumulation and EMT/cancer cell migration has been well established in both hypoxic and normoxic conditions." (PMID 33374849, 2020). "Moreover, the elevated level of PA enhances hypoxia-inducible factor 1-alpha (HIF1A) transcription which promotes angiogenesis and cancer cell proliferation." (PMID 32715369, 2020). "For example, GLUT1 was found in membranes of multifocally necrotizing cancer cells and in the cytoplasm of cancer cells with no necrosis, whereas HIF-1α mostly had a cytoplasmic location." (PMID 32252351, 2020). "As hypoxia is an inherent feature of solid tumors it is perhaps not surprising that HIF1α plays a major role in the pathophysiology of cancer." (PMID 33088284, 2020). "It is therefore recommended to study, in a meet step, natural and non-toxic MDR1 and HIF-1α blockers, which are able to potentialize the efficacy of anticancer drugs in cancer cells, especially of pancreatic or hepatic origin." (PMID 33052979, 2020). "Cancer studies have shown that HAND2-AS1 may inhibit cancer cell apoptosis by interacting with apoptosis-related molecules, such as HIF1α." (PMID 32411303, 2020). "A meta-analysis of 31 OC showed that the level of HIF-1α expression correlated with worse OS, worse disease-free survival (DFS), progression-free survival (PFS), cancer-specific survival (CSS), relapse-free survival (RFS), and worse metastasis-free survival (MFS)." (PMID 33327450, 2020). "In contrast, however, activation of the ERK/HIF-1α/EMT signaling was not induced by XCL1 in the other types of cancer cells such as A549 and Panc1 cells." (PMID 33374849, 2020).